DHRS9 (dehydrogenase/reductase 9)
Diseases named in the same sentence as DHRS9 in open-access papers:
DHRS9 is named in the same sentence as 38 diseases in open-access papers, as found by Europe PMC text mining. Sharing a sentence is not in itself a finding about the gene and the disease. The quoted sentences say what the papers report.
colorectal cancer (5 papers, 2016 to 2023). A primary or metastatic malignant neoplasm that affects the colon or rectum. "Actually, DHRS9 downregulation has been correlated with poor survival in oral squamous cell carcinoma and colorectal cancer patients, but those who received any anti-cancer therapy were excluded in these two studies." (PMID 36277959, 2022). "Studies have demonstrated that DHRS9 has a key function in colorectal cancer." (PMID 36340269, 2022). "Dehydrogenase/reductase (SDR family) member 9 (DHRS9) is aberrantly expressed in colorectal cancer (CRC), but its prognostic value is unknown." (PMID 26254099, 2016). "In addition, DHRS9 has been found to be abnormally expressed in colorectal cancer, but the regulatory mechanism of DHRS9 in colon cancer has not been thoroughly studied." (PMID 36340269, 2022).
epilepsy (4 papers, 2020 to 2025). A brain disorder characterized by episodes of abnormally increased neuronal discharge resulting in transient episodes of sensory or motor neurological dysfunction, or psychic dysfunction. "WES performed on a girl with early onset epilepsy revealed that she had a compound heterozygote for two novel missense mutations of the DHRS9 gene likely to disrupt protein function." (PMID 38256219, 2024). "Whole-exome sequencing performed on a girl with an early onset epilepsy revealed that she was a compound heterozygote for two novel missense mutations of the DHRS9 gene likely to disrupt protein function." (PMID 32752300, 2020). "Importantly, mutations in the DHRS9 gene resulting in amino acid substitutions S202L and D286H have been linked to an early-onset case of epilepsy; whether these mutations affect the function of DHRS9 has not been investigated." (PMID 40945732, 2025). "Another undeniable advantage of using WES is the possibility of identifying new possible candidate genes; the present study led to the identification of three genes never before related to epilepsy, namely, KCNC2, STXBP6 and DHRS9." (PMID 38256219, 2024).
colon cancer (3 papers, 2016 to 2024). "Moreover, promoting FXR expression in colon cancer cells could partially reverse the biological function changes caused by silencing DHRS9 expression." (PMID 36340269, 2022). "Cell experiments demonstrated that FXR activated DHRS9 to inhibit the malignant behaviors of colon cancer." (PMID 36340269, 2022). "FXR inhibited the oxidative phosphorylation and inhibited the malignant progression of colon cancer cells via targeting DHRS9." (PMID 36340269, 2022). "qRT-PCR results also showed that DHRS9 expression was remarkably lowered in colon cancer cell lines compared with normal colon epithelial cells." (PMID 36340269, 2022). "In conclusion, transcription factor FXR inhibited the malignant progression of colon cancer cells by activating DHRS9." (PMID 36340269, 2022). "In subsequent study, our team plans to establish mouse models to further verify the role of FXR/DHRS9 in regulating colon cancer progression at animal and clinical levels." (PMID 36340269, 2022). "The effect of FXR/DHRS9 axis on the malignant progression of colon cancer cells was further confirmed by rescue experiments." (PMID 36340269, 2022). "In this study, transcription factor FXR was found to regulate the malignant progression of colon cancer by activating target gene DHRS9, thereby inhibiting oxidative phosphorylation." (PMID 36340269, 2022). "Further bioinformatics analysis showed a significant reduction in DHRS9 expression in colon cancer tissues compared to normal tissues." (PMID 36340269, 2022). "We first verified the transfection efficiency of colon cancer cells by qRT-PCR and found that FXR overexpression partially offsets the increase of cell proliferative ability and colony forming ability induced by DHRS9 silencing in colon cancer cells." (PMID 36340269, 2022). "Consistent with the data from the adenoma and carcinoma samples, they found that colon-cancer-derived cell lines expressed low or undetectable levels of DHRS9 and displayed poor conversion of retinol to retinoic acid when compared to normal epithelial cells." (PMID 26254099, 2016). "Based on previous studies, we first examined the protein expression of oxidative phosphorylation genes in colon cancer cells and revealed that FXR overexpression partially offset the upregulation of oxidative phosphorylation genes caused by DHRS9 expression inhibition." (PMID 36340269, 2022). "Combined with the OCR measurement of cells and related rescue experiments, we finally determined that transcription factor FXR could activate DHRS9 to inhibit oxidative phosphorylation of colon cancer." (PMID 36340269, 2022). "Since the changes in the expression of FXR and DHRS9 in colon cancer cells led to changes in the expression of oxidative phosphorylation gene proteins, we then examined whether these changes lead to alternation in oxidative phosphorylation function." (PMID 36340269, 2022). "However, the association of DHRS9 expression with malignant progression of colon cancer has not been explored." (PMID 36340269, 2022). "As the lack of retinoic acid biosynthesis is considered to be a mechanism leading to the development of colorectal adenocarcinoma, we hypothesized that there may be a correlation between the dysregulation of DHRS9 expression and the invasiveness of colon cancer." (PMID 36340269, 2022). "Besides, DHRS9 was a downstream gene of FXR, and FXR/DHRS9 inhibited the deterioration of colon cancer through inhibiting oxidative phosphorylation." (PMID 36340269, 2022).
Obesity (3 papers, 2016 to 2024). Accumulation of substantial excess body fat. "Considering that human DHRS9 mRNA has a broad tissue distribution pattern, and the expression of DHRS9 is frequently altered during tissue inflammation and/or carcinogenesis as well as in metabolic disorders and obesity, we reinvestigated the substrate specificity of human and rodent DHRS9." (PMID 34953854, 2022). "We detected five genes were different expressed, YWHAQ, NCF2, DHRS9 and SCNA only up-regulation in PCOS-obesity patients with no significance different between control and PCOS-nonobesity patients." (PMID 27056885, 2016). "YWHAQ, NCF2, DHRS9 and SCNA were up-regulation in PCOS-obesity patients with no significance different between control and PCOS-nonobesity patients, which may be activated by lower DNA methylaiton." (PMID 27056885, 2016).
pancreatic cancer (3 papers, 2022). "DHRS9 is significantly overexpressed in pancreatic cancer tissues, and the high expression of DHRS9 is positively correlated with vascular infiltration level and associated with poor prognosis." (PMID 36340269, 2022). "Moreover, in pancreatic cancer, DHRS9 overexpression has been correlated with poor prognosis, implying that DHRS9 may play an oncogenic role based on distinct contexts." (PMID 36277959, 2022).
atherosclerosis (2 papers, 2024 to 2025). A disease characterized by the build-up of fatty material and calcium deposition in the arterial wall resulting in partial or complete occlusion of the arterial lumen. "As regard to arteriosclerosis, research has pinpointed protein tyrosine phosphatase receptor type J (PTPRJ) and dehydrogenase/reductase 9 (DHRS9) as pivotal biomarkers with high diagnostic accuracy for the pathological process of atherosclerosis." (PMID 40809841, 2025). "Hsa-miR-6890-5p regulates dehydrogenase/reductase 9 (DHRS9), a significant biomarker for atherosclerosis." (PMID 38601162, 2024).
breast carcinoma (2 papers, 2022 to 2025). "Cathepsin E can mediate the effects of APBB1IP, NT5C3B, and ZNF66 on HER2-negative breast cancer, as well as the effects of DHRS9, CDK12, and CD247 on HER2-positive breast cancer." (PMID 39944834, 2025). "CDK12 can promote the occurrence of HER2-positive breast cancer by promoting the expression of cathepsin E, and DHRS9 and CD247 can protect against HER2-positive breast cancer by reducing cathepsin E expression." (PMID 39944834, 2025). "For example, the mRNA signatures ETFDH, EGF, PRKAB1, ALOX5, DHRS9, MTHFR, and MGHH are in the maximum interaction network and are connected to other breast-cancer-related, frequently altered genes." (PMID 36551179, 2022).
cicatricial alopecia (2 papers, 2019 to 2022). Scarring hair loss, also known as cicatricial alopecia, is the loss of hair which is accompanied with scarring. "DHRS9 also increased in the hair follicles of patients with central centrifugal cicatricial alopecia." (PMID 31525235, 2019).
lymph node metastasis (2 papers, 2016 to 2022). "Patients with low DHRS9 expression level have significantly shorter disease-free survival and significantly increased lymph node metastasis and disease recurrence." (PMID 36340269, 2022). "Decreased expression of DHRS9 was significantly correlated with increased lymph node metastasis (p = 0.032), advanced tumor–node–metastasis (TNM) stage (p = 0.021), increased disease recurrence (p = 0.001), and death (p = 0.014)." (PMID 26254099, 2016). "Reduced expression of DHRS9 was significantly correlated with increased lymph node metastasis (p = 0.032), advanced TNM stage (p = 0.021), increased disease recurrence (p = 0.001), and death (p = 0.014)." (PMID 26254099, 2016). "In addition, reduced expression of DHRS9 was significantly correlated with a variety of important clinicopathologic parameters including lymph node metastasis, TNM stage, disease recurrence, and vital status." (PMID 26254099, 2016).
rectal cancer (2 papers, 2022 to 2024). A primary or metastatic malignant neoplasm that affects the rectum. "Specifically found in the intestine and significantly upregulated among CCRT-resistant rectal cancer patients (log2 ratio = 1.3317, p = 0.0001), the DHRS9 gene was selected for further analysis." (PMID 36277959, 2022). "Employing immunohistochemical staining, we also demonstrated that high DHRS9 immunoexpression is considerably associated with an aggressive clinical course and CCRT resistance in our rectal cancer cohort." (PMID 36277959, 2022). "In this study, we identified that DHRS9 is the most significantly upregulated gene related to epithelial cell differentiation among CCRT-resistant rectal cancer patients." (PMID 36277959, 2022). "Since DHRS9 has been considered as a moonlighting protein, we carried out a gene coexpression analysis to forecast the unidentified functions of DHRS9 in rectal cancer." (PMID 36277959, 2022). "Also, the representative images of IHC staining revealed that the immunoexpression of DHRS9 was remarkably higher in rectal cancer patients with CCRT resistance." (PMID 36277959, 2022). "Interestingly, in the present study, we identified DHRS9 as the most significantly upregulated gene in relation to epithelial cell differentiation among CCRT-resistant rectal cancer patients." (PMID 36277959, 2022). "Collectively, DHRS9 expression may assist decision-making for rectal cancer patients who underwent neoadjuvant CCRT." (PMID 36277959, 2022). "Dehydrogenase/reductase 9 (DHRS9) overexpression is correlated with a poor response to concurrent chemoradiotherapy and a poor prognosis in rectal cancer patients." (PMID 39233332, 2024). "Nevertheless, the correlations among DHRS9 expression, GAGs, especially keratan sulfate, and CCRT resistance in rectal cancer patients need to be further investigated." (PMID 36277959, 2022). "As a consequence, we intended to appraise the utility of DHRS9 expression status on CCRT efficacy, clinicopathological features, and patient prognosis in our rectal cancer cohort." (PMID 36277959, 2022). "In our rectal cancer cohort, we also demonstrated that high DHRS9 immunoexpression is remarkably linked to poor therapeutic response to CCRT and inferior patient survival, suggesting that epithelial cell differentiation may play a role in reducing CCRT efficacy in patients with rectal cancer." (PMID 36277959, 2022). "Consequently, the current study intended to connect DHRS9 expression to CCRT efficacy and patient survival and illuminate the role of DHRS9 in rectal cancer patients undergoing neoadjuvant CCRT." (PMID 36277959, 2022). "Using a transcriptome dataset, we focused on differentially expressed genes in relation to epithelial cell differentiation and then identified that the dehydrogenase/reductase 9 (DHRS9) gene level was the most considerably upregulated among CCRT nonresponders in rectal cancer." (PMID 36277959, 2022).
rheumatoid arthritis (2 papers, 2019 to 2022). A chronic, systemic autoimmune disorder characterized by inflammation in the synovial membranes and articular surfaces. "It is also worth noting that, even though DHRS9 could not be confirmed as a biomarker of vitD3-tolDC from MS patients, this does not mean that it could not still be useful in cells generated from patients with a different autoimmune disease, such as rheumatoid arthritis or type 1 diabetes." (PMID 31293564, 2019).
acute promyelocytic leukemia (1 paper, 2020). An aggressive form of acute myeloid leukemia (AML), characterized by arrest of leukocyte differentiation at the promyelocyte stage, due to a specific chromosomal translocation t(15;17) in myeloid cells. "Studies have shown that DHRS9 is involved in the biosynthesis of all trans-retinoic acid and exerts an anti-tumour role by inhibiting the proliferation of tumour cells, including acute promyelocytic leukemia, squamous cell carcinoma, neurocytoma and hepatocellular carcinoma." (PMID 33287740, 2020).
colon adenoma (1 paper, 2016). An adenoma that arises from the colon. "Since lack of retinoic acid biosynthesis has been proposed as a mechanism contributing to the development of colon adenomas and carcinomas, we hypothesized that dysregulation of DHRS9 expression may be associated with aggressive clinical behavior of CRC." (PMID 26254099, 2016). "Using microarray and reverse transcriptase-PCR analysis, they demonstrated that DHRS9 was frequently and significantly downregulated in colon adenomas and carcinomas as compared with normal colon tissues." (PMID 26254099, 2016).
colorectal adenocarcinoma (1 paper, 2022). The most common type of colorectal carcinoma. "The top two hundred differentially expressed genes showing positive correlations or negative correlations with DHRS9 were obtained from the colorectal adenocarcinoma dataset (n = 594, PanCancer Atlas, TCGA)." (PMID 36277959, 2022).
emphysema (1 paper, 2021). "KRT17 and DHRS9 were found to take part in the pathogenesis of emphysema." (PMID 34277700, 2021).
glioma (1 paper, 2024). A benign or malignant brain and spinal cord tumor that arises from glial cells (astrocytes, oligodendrocytes, ependymal cells). "ADH4, DHRS3, LRAT, RDH10, RDH12, and RDH5 were higher expressed in the high-glioma-risk group while DHRS9 was lower expressed." (PMID 39465792, 2024). "Ultimately, ADH4, DHRS3, DHRS9, LRAT, RDH10, RDH12, and RDH5 were selected as prognostic genes for building an RA metabolism–related prognostic signature with glioma." (PMID 39465792, 2024). "The prognostic signature comprised of ADH4, DHRS3, DHRS9, LRAT, RDH10, RDH12, and RDH5 based on RA metabolism was established, which provided a theoretical basis and reference value for the research of glioma." (PMID 39465792, 2024). "We identified 7 promising prognostic genes (ADH4, DHRS3, DHRS9, LRAT, RDH10, RDH12, and RDH5) within glioma and developed a prognostic model with significant predictive accuracy." (PMID 39465792, 2024).
rectal adenocarcinoma (1 paper, 2022). "Associations between DHRS9 expression and clinicopathological features in 172 rectal adenocarcinoma patients undergoing neoadjuvant CCRT." (PMID 36277959, 2022). "We also demonstrated that high DHRS9 immunoexpression is considerably associated with an advanced disease stage, CCRT resistance, and inferior prognosis in patients with rectal adenocarcinoma." (PMID 36277959, 2022).
tongue squamous cell carcinoma (1 paper, 2026). A squamous cell carcinoma that arises from the tongue. "Another gene involved in immune regulation and associated with poor prognosis in tongue squamous cell carcinoma is DHRS9." (PMID 41467516, 2026).
uveitis (1 paper, 2025). An inflammatory process affecting a part of or the entire uvea. "Several metaDEGs from the uveitis only group, including IFIT3, IFI44, IFITM1, MX1, TLR7 and DHRS9, and gene hubs from the modular co-expression analyses of the systemic disease-associated uveitis group are critical players in interferon-induced immune responses." (PMID 40270958, 2025).
cancer (7 papers, 2016 to 2025). A tumor composed of atypical neoplastic, often pleomorphic cells that invade other tissues. "Since atRA has been reported to exert tumor-suppressive functions in various cancer types, DHRS9, implicated in the biosynthesis of atRA, may be considered to have antitumor activities." (PMID 36277959, 2022). "In the cellular lipid metabolism process, Bacteroides_sartorii was positively correlated with lipid metabolism-related gene of Mttp, cancer-related genes of Rbp2, and Dhrs9, but was also negatively correlated with cancer-related genes of Neu1 and Hmgcs2." (PMID 39727670, 2025). "Many E2 regulated genes in other normal and cancer cell types were also regulated in MOE cells including Pgr, Greb1, Csf2, and Dhrs9, while other E2 regulated genes in MCF7 cells were not regulated (Nrip1) or even expressed (Tff1) in MOE cells." (PMID 26879975, 2016). "Moreover, low DHRS9 expression has been indicated to be correlated with poor prognosis in CRC patients, but those who received any anti-cancer therapy were excluded." (PMID 36277959, 2022).
tumor (7 papers, 2016 to 2025). "Especially, tumors with high DHRS9 immunoexpression (H-scores were above or identical to the median of all scored cases) had a considerably lower grade of tumor regression (p < 0.001)." (PMID 36277959, 2022). "Our results suggest that decreased expression of DHRS9 correlates with tumor progression and may serve as a potential prognostic biomarker in CRC." (PMID 26254099, 2016). "These preliminary findings also support a tumor inhibitory role of DHRS9 in human CRC." (PMID 26254099, 2016). "Moreover, in multivariate analysis, DHRS9 still emerged as a significant independent predictor of survival in addition to tumor stage." (PMID 26254099, 2016). "Our results demonstrated that decreased expression of DHRS9 correlates with tumor progression and might serve as an independent unfavorable prognostic indicator for patients with CRC." (PMID 26254099, 2016). "High DHRS9 immunoexpression was remarkably connected to advanced pre-CCRT and post-CCRT tumor status (p = 0.032 and p < 0.001), post-CCRT lymph node involvement (p = 0.042), and vascular invasion (p = 0.005)." (PMID 36277959, 2022).
DHRS9 also shares sentences with these, for which no sentence is quoted: oral squamous cell carcinoma (2 papers); adenoma (1); arteriosclerosis (1); atrial fibrillation (1); autoimmune disease (1); COVID-19 (1); heart failure (1); hepatocellular carcinoma (1); metabolic disorders (1); neurocytoma (1); polycystic ovary syndrome (1); psoriasis (1); Sepsis (1); squamous cell carcinoma (1); thyroid cancer (1); type 1 diabetes (1); type 2 diabetes (1).